MACO1 (macoilin 1)
Description:
Plays a role in the regulation of neuronal activity.
Synonyms: TMEM57; FLJ10747; MACOILIN
Tractability: Antibody: UniProt predicts a signal peptide or a membrane-spanning region. PROTAC: ubiquitination databases record sites on it.
Gene: Protein-coding gene on chromosome 1 (25,430,853 to 25,500,209, forward strand). Ensembl gene ENSG00000204178.
Subcellular location: Nucleus membrane; Cell projection, axon; Rough endoplasmic reticulum membrane
Subcellular location (Human Protein Atlas): Cytosol
Pathways (Reactome):
Signal Transduction: RHOA GTPase cycle; RHOC GTPase cycle
Gene Ontology:
Molecular function: protein binding; microtubule binding
Biological process: neuronal signal transduction; chemotaxis; brain development
Cellular component: rough endoplasmic reticulum membrane; neuron projection terminus; nuclear membrane; nucleus; synapse; axon; neuron projection
Genetic constraint (gnomAD): Loss-of-function variants: 14 observed, 75.68 expected, observed/expected ratio (o/e) 0.18, 90% interval 0.12 to 0.29. The upper end of that interval is the gene's LOEUF score, 0.29, which puts it in group 1 of 6, group 1 being the genes least tolerant of losing a copy. Missense variants: 501 observed, 799.94 expected, observed/expected ratio (o/e) 0.63, 90% interval 0.58 to 0.67. Synonymous variants: 288 observed, 301.29 expected, observed/expected ratio (o/e) 0.96, 90% interval 0.87 to 1.05.
Homologues: Orthologues: chimpanzee MACO1 (100% identical), dog MACO1 (100% identical), guinea pig MACO1 (100% identical), macaque MACO1 (100% identical), pig MACO1 (99% identical), mouse Maco1 (99% identical), rat Maco1 (99% identical), rabbit MACO1 (96% identical), tropical clawed frog maco1 (90% identical), Drosophila melanogaster CG30389 (44% identical), zebrafish si:dkey-12h9.6 (42% identical), Caenorhabditis elegans maco-1 (29% identical), and 1 more.
Diseases named in the same sentence as MACO1 in open-access papers:
MACO1 is named in the same sentence as 7 diseases in open-access papers, as found by Europe PMC text mining. Sharing a sentence is not in itself a finding about the gene and the disease.
MACO1 shares sentences with these, for which no sentence is quoted: breast carcinoma (1 paper); cardiac disease (1); coronary heart disease (1); heart failure (1); hyperlipidemia (1); Obesity (1); psoriasis (1).